AIF1 (allograft inflammatory factor 1)
Description:
Actin-binding protein that enhances membrane ruffling and RAC activation. Enhances the actin-bundling activity of LCP1. Binds calcium. Plays a role in RAC signaling and in phagocytosis. May play a role in macrophage activation and function. Promotes the proliferation of vascular smooth muscle cells and of T-lymphocytes. Enhances lymphocyte migration. Plays a role in vascular inflammation.
Synonyms: AIF-1; IBA1; IRT-1; Em:AF129756.17; IRT1
Tractability: Antibody: UniProt places it where antibodies can reach, with medium confidence; its Gene Ontology location is reachable by antibodies, with medium confidence. PROTAC: ubiquitination databases record sites on it; its protein half-life has been measured.
Gene: Protein-coding gene on chromosome 6 (31,615,217 to 31,617,021, forward strand). Ensembl gene ENSG00000204472.
Subcellular location: Cytoplasm, cytoskeleton; Cell projection, ruffle membrane; Cell projection, phagocytic cup
Subcellular location (Human Protein Atlas): Cytosol
Gene Ontology:
Molecular function: actin filament binding; protein binding; calcium ion binding
Biological process: actin filament bundle assembly; actin filament polymerization; cellular response to oxidative stress; cellular response to type II interferon; negative regulation of smooth muscle cell chemotaxis; negative regulation of smooth muscle cell proliferation; positive regulation of cell migration; positive regulation of cell population proliferation; positive regulation of chemokine production; positive regulation of chemotaxis; positive regulation of fibroblast growth factor production; positive regulation of G1/S transition of mitotic cell cycle; positive regulation of interleukin-6 production; positive regulation of monocyte chemotaxis; positive regulation of mononuclear cell migration; positive regulation of smooth muscle cell chemotaxis; positive regulation of smooth muscle cell proliferation; positive regulation of T cell migration; positive regulation of T cell proliferation; regulation of gene expression; actin crosslink formation; inflammatory response; microglial cell activation; parallel actin filament bundle assembly; phagocytosis, engulfment; and 2 more
Cellular component: actin filament; cytoplasm; cytosol; nucleus; perinuclear region of cytoplasm; ruffle membrane; lamellipodium; phagocytic cup; ruffle; cytoskeleton
Genetic constraint (gnomAD): Loss-of-function variants: 20 observed, 20.64 expected, observed/expected ratio (o/e) 0.97, 90% interval 0.68 to 1.41. The upper end of that interval is the gene's LOEUF score, 1.41, which puts it in group 5 of 6, group 1 being the genes least tolerant of losing a copy. Missense variants: 158 observed, 177.27 expected, observed/expected ratio (o/e) 0.89, 90% interval 0.78 to 1.02. Synonymous variants: 52 observed, 68.49 expected, observed/expected ratio (o/e) 0.76, 90% interval 0.61 to 0.96.
Homologues: Orthologues: chimpanzee AIF1 (99% identical), macaque AIF1 (99% identical), guinea pig AIF1 (95% identical), pig AIF1 (94% identical), rabbit AIF1 (92% identical), dog AIF1 (90% identical), mouse Aif1 (89% identical), rat Aif1 (86% identical). Paralogues in human: AIF1L (65% identical).
Diseases named in the same sentence as AIF1 in open-access papers:
AIF1 is named in the same sentence as 335 diseases in open-access papers, as found by Europe PMC text mining. Sharing a sentence is not in itself a finding about the gene and the disease. The quoted sentences say what the papers report.
Stroke (186 papers, 2010 to 2026). Sudden impairment of blood flow to a part of the brain due to occlusion or rupture of an artery to the brain. "Stroke-associated inflammation was attenuated, evidenced by reduced Tnf, Nlrp3 and Aif1 expression." (PMID 42229070, 2026). "During the acute phase post‐stroke, AIF1+ cells exhibited a hypertrophic and elongated morphology, indicative of increased cell reactivity." (PMID 39703181, 2025). "The results showed that AIF-1 gene expression was similar between the stroke group (0.018-fold) and the control group (0.0192-fold)." (PMID 39338346, 2024). "In the peri-lesional area of human stroke victims we noted numerous phagocytic microglia expressing AIF1 (red), co-localized with HTR2B-expressing neurons (green)." (PMID 27013593, 2016). "In addition, we found significant upregulation of Apoe and Lyz2, while Aif1 level appeared only slightly increased in MG in aged stroke compared to young stroke." (PMID 36824976, 2023). "Already during the phase of early acute inflammation at 24 h post-stroke, ADA-409-052 suppressed the stroke-induced expression of Gfap in the ipsilateral peri-ischemic area (from 1.059 ± 0.397 to 0.793 ± 0.197; p < 0.05), while the expression of Aif1 remained unchanged at the given time point." (PMID 33568697, 2021). "Eight protein-disease pairs were ranked as the most valuable findings after the filtering, which include IL-7R and TNFSF12 level on asthma; ACE level on COPD; AIF1 level on HF; SERPINF1 level on stroke; and SERPINE2, F11, KLKB1, and ABO level on VTE." (PMID 36388766, 2022). "Three of the 16 observational associations passed FDR < 0.05 in this analysis, which included ACE level on COPD, AIF1 level on HF, and SERPINF1 on stroke." (PMID 36388766, 2022). "Considering recent studies pointing towards sexual dimorphism in glial cell responses after stroke, we further investigated the possible relationships between GPR17+, AIF1+, and GFAP+ cells within the PI area of chronic lesions by performing sex‐specific correlation analyses on our cases." (PMID 39703181, 2025).
glioma (105 papers, 2011 to 2026). A benign or malignant brain and spinal cord tumor that arises from glial cells (astrocytes, oligodendrocytes, ependymal cells). "Consistent with the findings in human gliomas, Spp1, Aif1 and Ccl3 mainly expressed in glioma-associated macrophages, hemostatic microglia and activated microglia, respectively." (PMID 38515213, 2024). "Although the traditional M1 and M2 classifications are considered to be related to the prognosis of patients with gliomas, recent single-cell sequencing revealed that glioma-associated macrophages can be further classified more precisely, such as AIF1+TAMs, SPP1+TAMs and CCL3+TAMs49." (PMID 40898016, 2025). "The involvement of Iba1/AIF1 molecules in glioma progression, particularly in glioblastoma, is supported by accumulating evidence." (PMID 40361384, 2025). "AIF1 expression is positively correlated with immune infiltration in gliomas, esophageal cancers, and medulloblastomas." (PMID 41122966, 2025). "Taken together, the involvement of Iba1/Aif1 molecules in glioma progression highlights their role in creating an environment that supports tumor growth and suggests their potential as a therapeutic target." (PMID 40361384, 2025). "This correlation indicates the potential involvement of AIF1 in tumor immunosuppression, leading to the inhibition of immune responses against gliomas." (PMID 38521928, 2024). "Therefore, the dysregulated AIF-1 expression has been strongly linked to a range of diseases, including cardiac allograft vasculopathy, rheumatoid arthritis, hemangioma, gastric cancer, glioma, malignant breast tumor, pancreatic carcinoma, and hepatocellular carcinoma." (PMID 37014322, 2023). "In patients with brain glioma, including low-grade glioma and glioblastoma multiforme, AIF1 expression is upregulated." (PMID 37237507, 2023). "Subsequently, a lipopolysaccharide (LPS)-induced mouse encephalitis model was established, and significant allograft inflammatory factor 1 (IBA1) expression was detected in and around the glioma tissue." (PMID 37475025, 2023). "As a result, several studies have linked the expression and function of AIF1 to the development of cancer, with the best-studied cancer types being hepatocellular carcinoma (HCC), breast cancer and glioma." (PMID 37237507, 2023). "Our results align closely with previous studies of AIF-1 expression in human and rat macrophages infiltrating glioma tissue and mouse macrophages in a model of breast cancer metastasis." (PMID 36520870, 2022). "A similar strong correlation of AIF1-expressing macrophages/microglial cells with malignancy has been previously observed for human gliomas (Deiningeret al., 2000)." (PMID 33824914, 2021). "Through high-throughput expression profiling, WGCNA, lasso, and multivariate Cox analysis, we acquired eight genes (HCK, HAVCR2, CD37, LPAR5, NAGA, C1QC, FCER1G and AIF1) to construct the MRGs signature in Grade II/III glioma patients." (PMID 33186124, 2020). "Previous reports have suggested that AIF-1 could be a valuable prognostic biomarker for patients with glioma." (PMID 37014322, 2023). "In addition, our findings revealed a correlation between the methylation levels of AIF-1 and dysfunctional T-cell phenotypes in the glioma, uveal, ovarian, head and neck cancer, DLBC, breast cancer, and endometrial cancer cohorts." (PMID 37014322, 2023). "We then performed clustering on the TAM subsets from the 17 cross-grade glioma patients and found three major TAM subsets with distinguished expression of CCL3, AIF1, and SPP1 respectively, the three subsets also share most of the marker genes with the previously identified TAMs in grade 2 glioma." (PMID 38515213, 2024). "Interestingly, the AIF1+TAM and SPP1+TAM were significantly more prevalent in grade 4 GBM compared to grade 2/3 gliomas." (PMID 38515213, 2024). "Furthermore, allograft inflammatory factor-1 (AIF-1) and heme oxygenase-1 (HO-1) can also be used to define a distinct subset of GAMs in rat and human gliomas." (PMID 23983766, 2013).
glioma (continued). "Notably, we observed an abundance of Aif1, Met, and Fosl1 expressing cells not exclusively in hypoxic regions but also in the perivascular space of Pdgfbret/ret glioma sections, indicating a putative opportunistic occupation and exploitation of this glioma niche vacated by pericytes." (PMID 41339360, 2025).
ischemia (93 papers, 2008 to 2025). A hypoperfusion of the BLOOD through an organ or tissue caused by a PATHOLOGIC CONSTRICTION or obstruction of its BLOOD VESSELS, or an absence of BLOOD CIRCULATION. "For subsequent experiments, we chose to investigate the role of AIF-1 in ischemia injury in the native kidney." (PMID 39836477, 2025). "For instance, allograft inflammatory cytokine-1 (AIF-1) was observed to be significantly elevated after hepatic ischemia/reperfusion, which is consistent with the results of a previous report in a rat model." (PMID 33407080, 2021). "Increased numbers of AIF-1-immunoreactive macrophages/microglial cells were observed in brain tumors and ischemia as well as after SCI." (PMID 22348029, 2012). "Similar staining patterns of Nefl, Aif1, and Pecam1 were observed in the ischemia-affected striatum (data not shown)." (PMID 31089963, 2019).
Cerebral ischemia (51 papers, 2014 to 2025). Restriction of arterial blood supply to the brain associated with insufficient oxygenation to support the metabolic requirements of the tissue. "In a previous study, microglia was identified to react already 3.5 h after experimental focal cerebral ischemia lasting up to 7 days as visualized by immunolabeling of Iba1, encoded by Aif1." (PMID 31089963, 2019). "Research involving animal models has revealed that mice with the AIF1 gene suppressed exhibit a decrease in the size of brain lesions after temporary localized cerebral ischemia when compared to their genetically unmodified counterparts." (PMID 39087007, 2024).
Alzheimer disease (43 papers, 2012 to 2025). A progressive, neurodegenerative disease characterized by loss of function and death of nerve cells in several areas of the brain leading to loss of cognitive function such as memory and language. "In a study on Alzheimer’s disease, downregulation of PU.1 in BV2 cells suppressed the expression of pro-inflammatory genes, such as CCL2 and IL-1β, as well as Aif1 (also known as Iba1), a molecular marker of microglia." (PMID 34681723, 2021).
diabetes (43 papers, 2009 to 2025). "The TTC network findings suggest that hypothalamus Aif1 is associated with both obesity and diabetes." (PMID 19463160, 2009). "Interestingly, human sequence variants near the AIF1 locus associate with obesity and diabetes; in adipose samples from participants with obesity, we observe direct correlation of AIF1 and MAOA transcript levels." (PMID 36596796, 2023). "While studies in human populations suggest links between AIF1 and metabolic diseases such as obesity and diabetes, such associations with AIF1L have not been reported." (PMID 32107417, 2020).
Cognitive impairment (37 papers, 2015 to 2026). Abnormal cognition is characterized by deficits in thinking, reasoning, or remembering. "Aif1 and Tlr2 were the only genes significantly associated with spatial recognition memory, implying that bacterial lipoprotein content and microglial proliferation may be involved in diet-induced cognitive impairment." (PMID 32066702, 2020).
Obesity (35 papers, 2009 to 2026). Accumulation of substantial excess body fat. "Elevated AIF-1 levels correlate with inflammatory adipocytes and obesity, while reduced AIF-1 promotes weight loss through regulation of monoamine oxidase A and decreased leptin/resistin production." (PMID 41694567, 2026). "Population-based studies have associated sequence variants near the AIF-1 locus with obesity, though AIF-1's potential pathophysiological involvement remains uninvestigated." (PMID 41694567, 2026). "The authors observed that Allograft inflammatory factor-1 (AIF-1) deficiency, a protein preferentially expressed in myeloid cells, conferred strong protection against obesity induced by HFD, insulin resistance and increased energy expenditure in mice." (PMID 39405979, 2024). "Here, we show that loss of AIF1 protects against diet-induced obesity, glucose intolerance, and insulin resistance." (PMID 36596796, 2023). "In a study of 510 obese people, the single nucleotide polymorphism rs2844479 in the AIF1 gene was associated with an increased risk of obesity in the Greek population." (PMID 37237507, 2023). "Our studies have identified a striking resistance to obesity accompanied by improved glucose handling in mice deficient in AIF1, a protein preferentially expressed in cells of the myeloid lineage." (PMID 36596796, 2023). "These significant correlations with adipose AIF1 expression are in agreement with previous findings suggesting AIF1 is an adipokine associated with clinical parameters related to obesity." (PMID 30386176, 2018). "Hypothalamus Aif1 is also linked to Lta and Faim2, genes that regulate apoptosis and also reported as associated with obesity." (PMID 19463160, 2009). "Moreover, patients with obesity and hepatic dysfunction showed a large loss of microglia expressing AIF1." (PMID 37237507, 2023). "Because of the homology of these members of the AIF family and reported AIF1 associations with metabolism and obesity, we hypothesized that AIF1L might play a role in diet-induced obesity (DIO) and associated glucose insensitivity." (PMID 32107417, 2020). "To assess whether the association between AIF-1 mRNA levels and obesity was related to increased macrophage infiltration into adipose tissue, we wished to correlate AIF-1 levels to a macrophage marker." (PMID 24267103, 2013). "This review comprehensively examines AIF-1's involvement in inflammatory and metabolic pathogenesis, particularly focusing on obesity and inflammation." (PMID 41694567, 2026). "Through systematic literature analysis, we consolidated current knowledge on AIF-1's functions and analyzed studies exploring its roles in obesity, insulin resistance, and inflammation to clarify broader disease mechanisms." (PMID 41694567, 2026). "To evaluate possible links between the Aif1 locus and obesity, we compared the responses of WT and Aif1−/− mice to HFD feeding over 16 weeks." (PMID 36596796, 2023). "Our aim was to examine the expression of AIF-1 in human white adipose tissue (WAT) in relation to obesity and metabolic phenotypes in women." (PMID 24267103, 2013). "Collectively, our findings elucidate an AIF1–MAOA axis that affects NE catabolism in macrophages and suggest that it may contribute to obesity and associated insulin resistance and glucose intolerance." (PMID 36596796, 2023). "Collectively, AIF1 secreted by adipose-tissue macrophages is an important crosstalk mediator in the physiology of adipocytes, and AIF1 deregulation is involved in obesity, so it may be a potential therapeutic target for anti-obesity treatments." (PMID 37237507, 2023). "We link this phenotype to higher adipose NE levels that stem from decreased monoamine oxidase A (MAOA) expression and NE clearance by AIF1-deficient macrophages, and find through reciprocal bone marrow transplantation that donor Aif1-/- vs WT genotype confers the obesity phenotype in mice." (PMID 36596796, 2023).